RHOB (ras homolog family member B)
Diseases named in the same sentence as RHOB in open-access papers (continued):
Sharing a sentence is not in itself a finding about the gene and the disease.
gastric cancer (14 papers, 2014 to 2025). A primary or metastatic malignant neoplasm involving the stomach. "It is worth considering that, in gastric cancer cells, RhoA promotes cell proliferation and RhoC stimulates cell migration and invasion, while RhoB functions contrary to RhoA and/or RhoC." (PMID 32831016, 2020). "Ectopic expression of RhoA promotes proliferation and RhoC overexpression enhances motility and invasiveness of SGC7901 and AGS human gastric cancer cell lines, while RhoB overexpression suppresses these malignant phenotypes." (PMID 32392742, 2020). "Studies of patient biopsies revealed that RhoB expression levels are also dramatically decreased in bladder cancer, cervical cancer, colorectal cancer, gastric cancer, head and neck cancer, kidney cancer and pancreatic cancer." (PMID 29385717, 2018). "In addition, RHOB expression significantly suppresses the proliferation, migration, and invasion of gastric cancer cells while also increasing their sensitivity to anticancer drugs." (PMID 39495117, 2024). "In gastric cancer datasets, MT2A, TXNIP, FOS, RHOB, and GLUL emerged as the five most important mRNAs to predict exmiRs." (PMID 39495117, 2024). "RhoB plays an important role in the PI3K/AKT pathway, and studies have shown that RhoB mediates regulation of the PI3K/AKT pathway in gastric cancer cells, inhibiting invasion and migration by reducing the expression level of p-AKT." (PMID 31011573, 2019). "For example, miR-19a was reported to play oncogenic role in gastric cancer by targeting the tumor suppressor MXD1,in cervical carcinoma by targeting CUL5 and in pancreatic cancer by downregulating RHOB promote and." (PMID 29416742, 2018). "In recent study, RhoA and RhoC expression are elevated, while RhoB expression is downregulated or absent in gastric cancer tissues, compared to normal gastric tissues." (PMID 32392742, 2020).
breast tumors (11 papers, 2002 to 2023). "Although rare, primary GBM and breast tumors with PTEN splice mutations had significantly higher RHOB gene expression versus tumors with PTEN wt or other PTEN mutations." (PMID 34680293, 2021). "RhoA, RhoB, Rac1/Rac1b, and Cdc42 are overexpressed in breast tumors, with RhoA expression associated with advanced stages of the disease." (PMID 19703301, 2009). "Using expression data extracted from the TCGA project "Breast Invasive Carcinoma", we confirmed significant increase of the RhoA/RhoB expression ratio in triple negative breast tumors compared to other breast tumors (p<0.001)." (PMID 33162807, 2020). "Similar to the ERM protein family (i.e., ezrin and moesin), RhoA, RhoB and Cdc42 immunoreactivity was also observed in the stromal compartment of the breast tumour samples and its blood vessels." (PMID 23420497, 2013). "Similarly, DEGnext predicts upregulation of RHOB, which has been reported to exert positive effects during carcinogenesis of breast tumors." (PMID 34991439, 2022). "In addition, ATO inhibits the volume and weight of breast tumor in tumor-bearing mice and upregulated RhoB in tumor tissues." (PMID 31011573, 2019). "However, the cell-autonomous role of RhoB has yet to be studied in tumor angiogenesis, as RhoB signaling also functions as a tumor suppressor in breast tumors and therefore its vessel-specific function is difficult to tease apart." (PMID 31174284, 2019). "Further research found that RhoB inhibits the proliferation, invasion, EMT, and PTEN/AKT signal pathway in breast tumor cells." (PMID 31011573, 2019). "The expression of RHOB has not been described in endometriosis, but upregulation of this gene has been reported in human breast tumors." (PMID 38069001, 2023). "For breast tumours we found that there was only a tendency in the expression of rhoB, rhoC and rac1 mRNA, but not of rhoA mRNA, to increase with grading." (PMID 12237774, 2002).
colorectal cancer (11 papers, 2009 to 2025). A primary or metastatic malignant neoplasm that affects the colon or rectum. "In the context of cancer, CCL24 expression has been shown to associate with poor prognosis in colorectal cancer and also contribute to hepatocellular carcinoma malignancy via the RhoB-VEGFA-VEGFR2 angiogenesis pathway." (PMID 31649887, 2019). "RhoB was negatively associated with chemotherapy response and survival in colorectal cancers." (PMID 38355625, 2024). "Inhibition of miR-223 led to upregulation of RhoB and, in turn, promoted apoptosis of Colorectal cancer cells." (PMID 36138893, 2022). "RhoB knockdown using siRNA in human colorectal cancer cell line SW480 was carried out to further validate the effects of RhoB in vitro, and increased Muc2 and Ki67 protein levels in SW480 cells with RhoB knockdown were observed." (PMID 36114582, 2022). "RhoB is generally known to be a tumor suppressor gene, since RhoB inhibits cell proliferation, invasion, and tumor angiogenesis, and overexpression of RhoB induces apoptosis in colorectal carcinoma cells." (PMID 33406809, 2021). "Additionally, the knockdown of RhoB was found to enhance radiotherapy sensitivity in colorectal cancer." (PMID 39336777, 2024). "In some studies, RhoB exhibits oncogenic properties by promoting cell proliferation and growth, and reducing therapy response, resulting in poor clinical outcomes including primary tumor metastasis and short survival of patients including colorectal cancers." (PMID 38355625, 2024). "The expression of miR-21 is frequently upregulated in colorectal cancer, and the target genes regulated by miR-21 include PDCD4, RhoB, and TGFβR2." (PMID 40693022, 2025). "Genes characteristic of colorectal carcinoma were overexpressed in the FACS-purified cells (e.g., HOX2D and RHOB)." (PMID 19401702, 2009). "Furthermore, a study conducted on colorectal cancer cells utilized a luciferase assay to demonstrate that overexpression of miR-21 suppresses RHOB 3′-UTR luciferase-reporter activity, thereby preventing RHOB’s suppressive effect on cell proliferation." (PMID 31200451, 2019).
glioblastoma (11 papers, 2010 to 2024). The most malignant astrocytic tumor (WHO grade IV). "In glioblastoma cell lines, RHOB knockdown has been shown to cause decreased cytokine-induced STAT3 activation and impaired STAT3 activity." (PMID 38166692, 2024). "Another study showed an overactivation of protein kinase C in glioblastoma, which caused the repression of RhoB, enhancing cell motility and invasion." (PMID 32089990, 2020). "Glioblastoma-EV-delivered miR-30b-3p has been shown both in vitro and in vivo to decrease apoptosis and increase proliferation by directly targeting RHOB, offering a potential treatment strategy for glioblastoma." (PMID 38379858, 2024). "On the other side, EV-miR-30b-3p was reported to suppress RHOB expression in glioblastoma cells, and this promoted stemness and resistance to temozolomide (TMZ) in glioblastoma." (PMID 36674525, 2023). "The authors previously showed that inhibiting RhoB, using the dominant-negative mutant RhoBN19, in U87 human glioblastoma xenografts increased their radiosensitivity, partially by increasing the oxygenation in the tumors." (PMID 29385717, 2018). "Their results suggest that abnormal activation of the PI3K pathway in glioblastoma represses RhoB expression via PKCι activation, indicating PKCι as a potential drug target for glioblastoma therapy." (PMID 29385717, 2018). "RhoB depletion leads to cell cycle arrest, apoptosis and reduced tumorigenic potential of glioblastoma cells in vivo." (PMID 29385717, 2018). "However, new studies are challenging these findings, suggesting that RHOB is an oncogene since studies have shown that RHOB has a tumor-promoting role in glioblastoma." (PMID 31888022, 2019). "Conversely, they also demonstrate that RhoB constitutive expression can suppress PKCι activity, implying the two proteins could be mutually antagonistic and function as a switch for glioblastoma cell motility." (PMID 29385717, 2018). "Repression of RHOB has been shown to increase motility and invasion in glioblastoma cells." (PMID 26132659, 2015). "The PKCι-mediated uncoupling of Lgl from non-muscle myosin II is a second mechanism by which PKCι can regulate actin dynamics, as we have previously shown that PKCι negatively regulates the expression of RhoB in glioblastoma cells and can influence actin dynamics in this manner." (PMID 20815904, 2010).
non-small cell lung carcinoma (11 papers, 2018 to 2024). A group of at least three distinct histological types of lung cancer, including non-small cell squamous cell carcinoma, adenocarcinoma, and large cell carcinoma. "For example, in non-small cell lung cancer, miR-223-3p restrains the malignant biological behaviors of tumor cells and induces the apoptosis via directly targeting ras homolog family member B." (PMID 35965327, 2022). "Meanwhile, it recruits histone demethylase LSD1 to the RHOB promoter region and mediates H3K42 demethylation to silence RHOB, thus promoting non-small-cell lung cancer cell proliferation and invasion." (PMID 34819492, 2021). "Additionally, miR-223–3p could regulate the cellular apoptosis of non-small cell lung cancer by targeting RhoB." (PMID 36138893, 2022). "In non-small cell lung cancer (NSCLC), DUXAP8 promotes tumor cell proliferation and invasion through epigenetic silencing of Egr1 and RHOB." (PMID 34957112, 2021). "DUXAP8 was initially reported to promote non-small-cell lung cancer proliferation and invasion by epigenetically silencing EGR1 and RHOB." (PMID 32849765, 2020). "Recent studies indicated that DUXAP8 has a critical role in non-small-cell lung cancer cell proliferation and invasion by epigenetically silencing EGR1 and RHOB." (PMID 30367681, 2018). "The pseudogene DUXAP8 may act as an oncogene in non-small cell lung cancer, and it may play this role by silencing EGR1 and RHOB transcription via binding with EZH2 and LSD1." (PMID 33711952, 2021).
ovarian carcinoma (11 papers, 2010 to 2025). A malignant neoplasm originating from the surface ovarian epithelium. "The utilization of Trichostatin A (a class I/II HDAC inhibitor) on ovarian cancer cell lines induced a reactivation of the expression of RHOB associated with induction of apoptosis." (PMID 31200451, 2019). "Additionally, the decrease and loss of RHOB in ovarian cancer has been correlated with progression." (PMID 31200451, 2019). "Thus, it is proposed that RhoB loss of expression be a frequent event in ovary cancer progression, which may serve as a useful target for gene therapy of ovarian malignancy." (PMID 24223801, 2013). "Compared with healthy controls (HC), RHOB was significantly less expressed in smooth muscle cells, but significantly more expressed in dendritic cells (DC) and T cells in ovarian cancer (OV)." (PMID 39944833, 2025). "Murine studies have demonstrated the potential of RhoB restoration to suppress ovarian cancer xenografts and the chemotherapeutic agent gemcitabine has been shown to act on miR-19a, potentially inhibiting tumor growth by means of RHOB." (PMID 31200451, 2019). "Further, in vivo restoration of RhoB led to the suppression of tumorigenicity, providing evidence in favor of reactivation of the RhoB signaling pathway to enhance ovarian cancer therapy." (PMID 29385717, 2018). "RhoB expression is decreased or lost in ovarian carcinoma and decreases significantly with increasing grade." (PMID 29385717, 2018). "RHOB has been reported to be downregulated in various tumors including gastric, lung, and ovarian cancer, and its overexpression inhibits proliferation, migration, and invasion." (PMID 29290960, 2017). "Interference into Revivification of RhoB gene results in reduction of ovary carcinoma cell apoptosis." (PMID 24223801, 2013). "RhoB was strong expressed in normal ovary tissue, whereas in ovarian cancer the RhoB was significantly decreased with ovary carcinogenesis." (PMID 24223801, 2013). "Subsequently, RhoB expression is detected in normal ovary epithelium, borderline tumors, and decreases significantly or lost in the majority of ovarian cancer specimen (P<0.05)." (PMID 24223801, 2013). "In our study, RhoB was hardly expressed or lost in clinic ovary cancer, whereas RhoB gene was evidently up-regulated in SKOV3 and A2780 cells after treated with TSA." (PMID 24223801, 2013). "In this study, human ovary tumor tissue ranging from different histological types of tumor to invasive tumors was analyzed for RhoB, with normal ovary epithelium as control, which showed that RhoB expression decreases with the progression of ovary cancer." (PMID 24223801, 2013). "Here, expression of RhoB gene was evaluated in human benign, borderline and malignant ovary tumors by immunostaining, with normal ovary tissue as control." (PMID 24223801, 2013). "Poor differentiated tumors had a greater (80%) reduction in the expression of RhoB than medium differentiated (44% reduction) and well differentiated ovary cancer (28.5% reduction)." (PMID 24223801, 2013). "Moreover, ectopic expression of RhoB into nude mice is highly effective in suppressing tumor growth of ovarian cancer xenografts." (PMID 27259239, 2016). "TSA can both significantly revive the RhoB gene and mediate apoptosis of ovarian cancer cells, but 5-Aza couldn’t." (PMID 24223801, 2013). "More importantly, TSA could significantly increase the expression of RhoB and decresed cell proliferation of ovarian cancer cells." (PMID 24223801, 2013). "Additional researches are being conducted to evaluate the RhoB function in ovarian cancer progression and the potential use of this gene as a selectable target that could provide gene treatment options for patients with ovarian tumors." (PMID 24223801, 2013).
ovarian carcinoma (continued). "Further experiments will be developed with complementary ovarian carcinoma cell lines overexpressing HER-2 receptor to decipher the role of RhoB/PTEN cross-talk and/or expression vs the HER-2 expression level to increase our knowledge in ovarian carcinomas treatment." (PMID 20588279, 2010). "Recombinant adenovirus transduced with RhoB cDNA was shown to activate apoptosis in vitro, whereas injections of Ad-RhoB in nude mice with ovarian cancer xenografts demonstrated suppression of tumor growth in vivo, thereby illustrating that restoration of RhoB may prove useful in cancer treatment." (PMID 31200451, 2019). "However, RhoB gene self-silencing in ovary cancer cells was significantly reversed by TSA." (PMID 24223801, 2013). "However, our findings correlate well with CDC42 and RhoB expression levels found in the Ovarian cancer database of Cancer Science Institute Singapore (CSIOVDB), reporting significantly higher CDC42 and RhoB levels in OCCC compared to the other subtypes." (PMID 28611940, 2017). "Revivification of RhoB gene was investigated by analyzing the effect of histone deacetylase (HDAC) inhibitor trichostatin (TSA) and methyltransferase inhibitor 5-azacytidine (5-Aza) on ovarian cancer cells via RT-PCR and western blot." (PMID 24223801, 2013). "In our study, Epigenetic regulation of RhoB expression was investigated by analyzing the effect of histone deacetylase (HDAC) inhibitor trichostatin (TSA) and methyltransferase inhibitor 5-Azacytidine (5-Aza) on ovarian cancer SKOV3 and A2780 cells via RT-PCR and western blot." (PMID 24223801, 2013).
hepatocellular carcinoma (9 papers, 2011 to 2024). A malignant tumor that arises from hepatocytes. "In this study, we demonstrated that Cullin3-TNFAIP1 complex targeted RhoB for ubiquitination and subsequent proteasome-dependent degradation in hepatocellular carcinoma (HCC) cells." (PMID 33553178, 2021). "In addition, we demonstrated that downregulation of TNFAIP1 induced the expression of pro-inflammatory cytokines IL-6 and IL-8 in TNFα-stimulated hepatocellular carcinoma cells through the activation of p38/JNK MAPK pathway via blocking RhoB degradation." (PMID 33553178, 2021). "Moreover, RhoB was reported very recently to be targeted by miR-21 in hepatocellular carcinoma cell lines." (PMID 21347332, 2011). "Moreover, a very recently published study demonstrated an interaction between the 3′UTR of RhoB and miR-21 in a hepatocellular carcinoma cell line." (PMID 21347332, 2011). "HCC cell-derived sEVs that express miR-21-5p aggregates in macrophages directly target RhoB to promote M2 polarization in macrophages and promote hepatocellular carcinoma proliferation." (PMID 38690261, 2024). "In hepatocellular carcinoma (HCC) cells, CCL24, a chemotactic factor, was shown to promote migration and invasion via a RhoB-VEGFA signaling pathway." (PMID 29385717, 2018). "Moreover, a recent study performed in hepatocellular carcinoma cell lines demonstrated a direct interaction between miR-21 and the 3′UTR of RhoB, a gene that may be involved in angiogenesis regulation." (PMID 21347332, 2011).